SHH (sonic hedgehog signaling molecule)
Diseases named in the same sentence as SHH in open-access papers (continued):
Sharing a sentence is not in itself a finding about the gene and the disease.
medulloblastoma (continued). "Genomic studies in large series of primary medulloblastoma have led to a novel classification of medulloblastoma into different molecular subtypes, characterized by the activation of sonic hedgehog (SHH), Wnt/ β-catenin or c-Myc pathways (Group 3)." (PMID 25915540, 2015). "Previous studies have reported SHH-induced medulloblastoma formation in mouse models via activation of the Akt signaling pathway through Akt phosphorylation." (PMID 26345456, 2015). "Several studies in medulloblastoma show a connection between the miR-183 family and the sonic hedgehog (SHH) signaling pathway, which is involved in embryogenesis, and dysregulated in medulloblastomas." (PMID 26170234, 2015). "Constitutive activation of the SHH signaling pathway leads to defects in cell cycle exit, migration and differentiation which in turn can induce medulloblastoma." (PMID 26091048, 2015). "The expression of miR-17-92 is also induced by another member of the Myc family, N-myc, a target of the activation of the Sonic Hedgehog (SHH)/Patched signaling pathway in medulloblastoma." (PMID 26442266, 2015). "We previously showed that miR-17~92 expression is absolutely required for SHH medulloblastoma initiation and that its silencing inhibits medulloblastoma progression." (PMID 26091048, 2015). "Ectopic overexpression of all three miRs in cultured medulloblastoma cells from the Ptch1+/−/PtenFloxp/+ transgenic mice (Ptch1 is the receptor for SHH), increased proliferation." (PMID 26170234, 2015). "Further linking cAMP to SHH-mediated MB, another group of researchers found that ablation of the GNAS gene, encoding the G protein Gαs, is sufficient to initiate SHH medulloblastoma." (PMID 26512695, 2015). "Maximal tumor growth in murine and human models of SHH subtype medulloblastoma is dependent upon co-activation of SHH and the CXCR4 pathway." (PMID 26283963, 2015). "Studies targeting the regulator of PI3K, PTEN—whose loss is common in medulloblastoma—have shown innate resistance to SHH inhibitors in PTEN null medulloblastomas compared to PTEN wild-type medulloblastoma." (PMID 26345456, 2015). "To gain first insights into possible SERPINE2/PN-1 functions in medulloblastoma cells, we used a siRNA-based approach to lower its expression in human DAOY cells, which are a cellular model for SHH subgroup medulloblastomas." (PMID 25901736, 2015). "A relationship between the miRs and SHH was seen in medulloblastoma patients, in whom expression of the miR-183 family members was higher in SHH-negative compared to SHH-positive tumors." (PMID 26170234, 2015). "SHH medulloblastoma arise from GNPs with aberrant SHH signaling upon deletion of one copy of the SHH receptor Patched (Ptch1+/-) alone or with one or two copies of Cdkn2c." (PMID 26091048, 2015). "Constitutive activation of the SHH signaling pathway leads to defects in cell cycle exit, migration and differentiation, which, in turn, induce medulloblastoma (MB)." (PMID 24928431, 2014). "In murine tumor models, transcriptional profiling comparisons suggest that WNT and SHH-medulloblastoma arise during early embryonic development equivalent to the first 6 weeks of human embryogenesis." (PMID 25412507, 2014). "Of note, the expression of most WNT and SHH pathway members was significantly higher in WNT or SHH-medulloblastoma than in CD133+ NSCs." (PMID 25412507, 2014). "To assess their role in cerebellar and medulloblastoma (MB) development, we deleted the miR-17∼92 cluster family in Nestin-positive neural progenitors and in mice heterozygous for the Sonic Hedgehog (SHH) receptor Patched 1 (Ptch1+/−)." (PMID 24928431, 2014). "Currently, mutations in tumor suppressors PATCHED and SUFU of the SHH pathway as well as aberrant activation of CTNNB1, MYC, and the 17-92 cluster of microRNAs have been causatively linked to the etiology of medulloblastoma." (PMID 24970811, 2014).
medulloblastoma (continued). "This revealed that WNT and SHH subgroups clustered closest to NSCs and NPCs, indicating less variance between these medulloblastoma groups and embryonic cell types." (PMID 25412507, 2014). "Based on these data, we combined all AU-MB and SJ-MB specimens to generate molecular cohorts of WNT (n = 8), SHH (n = 21), Group 3 (n = 22) and Group 4 (n = 14) medulloblastoma for further subgroup-specific analyses." (PMID 25412507, 2014). "In this cohort, 36 of 42 medulloblastomas of the SHH methylation subgroup were diagnosed as DMB (desmoplastic medulloblastoma)/MBEN, 4 of the classic and 2 of the anaplastic subtype." (PMID 24791927, 2014). "Our data indicate that the expression profiles of SHH, Group 3 and Group 4 medulloblastoma are similar to cerebellar granule neuron gene expression signatures, but there are distinct differences in the specific pathways that are active." (PMID 25412507, 2014). "MicroRNAs encoded by the miR-17∼92 cluster, also called oncomiR-1, are overexpressed in various cancers including mouse and human medulloblastomas with constitutively activated SHH signaling." (PMID 24928431, 2014). "WNT and SHH medulloblastoma consistently clustered closer to embryonic-derived cell types, whereas Group 3 and Group 4 medulloblastoma clustered closer to foetal samples." (PMID 25412507, 2014). "The alignment of NSCs, NPCs, NFGM and NFB with WNT, SHH, Group 3 and Group 4 medulloblastoma was tested using gene signatures organized into functional genetic neighborhoods." (PMID 25412507, 2014). "Recent progress on medulloblastoma gene expression profiling demonstrated the disease is heterogeneous and consists of different molecular subgroups: SHH, WNT and Non-SHH/WNT medulloblastoma." (PMID 24932704, 2014). "The results of this study indicate that GPCR expression patterns delineate five groups of medulloblastoma tumors, two of which correlate with high fidelity to the WNT and the SHH subgroups of medulloblastoma." (PMID 24252460, 2013). "Strikingly, the highest frequencies of TERT mutations were observed in SHH (83 %; 55/66) and WNT (31 %; 4/13) medulloblastomas derived from adult patients." (PMID 24174164, 2013). "These prognostic implications were similar in adult medulloblastoma patients and in the adult SHH subgroup." (PMID 24174164, 2013). "Further, two of the tumor clusters correspond with high fidelity to the WNT and SHH subgroups of medulloblastoma." (PMID 24252460, 2013). "BMP-2 and -4 signaling antagonizes SHH-dependent proliferation by inducing the irreversible differentiation of cerebellar granule neuron progenitors (GNPs) and of medulloblastoma cells." (PMID 23527084, 2013). "“SHH-type” medulloblastomas originate from a distinct population of cells within the cerebellum - granule neuron precursors (GNPs) - in which the SHH pathway is persistently activated." (PMID 22808009, 2012). "This difference in anatomical preference was confirmed by examining medulloblastomas resected from children—SHH-subtype tumors were located within the cerebellum while WNT-subtype tumors were in the fourth ventricle and dorsal brainstem." (PMID 21427785, 2011). "Two distinct medulloblastoma subtypes have been differentiated based on molecular markers: tumors in which sonic hedgehog (SHH) signaling is dysregulated and tumors in which a different signaling pathway, driven by the transcription factor WNT, is disrupted." (PMID 21427785, 2011). "Over the last decade and a half, numerous investigations have implicated sonic hedgehog (SHH) signaling in medulloblastoma pathogenesis 21, 67, and modulation of the SHH pathway has led to the vast majority of the medulloblastoma GEMMs currently available." (PMID 19076778, 2009).
medulloblastoma (continued). "Mutations in Sonic Hedgehog (SHH) pathway genes (PTCH1, SUFU) are found in approximately 25% of medulloblastomas, and in WNT pathway genes (β-catenin, APC, AXIN) in approximately 15% of the cases." (PMID 18769486, 2008). "Conversely, SHH medulloblastoma mutants exhibited VAF near 50% in both WGS and RNA-seq reads." (PMID 39753768, 2025). "SHH pathway inhibitors, such as sonidegib, are being assessed in clinical trials for adult medulloblastoma, and the European trial EORTC 1634-BTG/NOA-23 is currently evaluating sonidegib as an adjunct to standard chemoradiotherapy in post-pubertal patients with SHH-active disease." (PMID 41257104, 2025). "For instance, medulloblastomas have been shown to activate RAS signaling via alterations in the SHH and WNT pathways, despite lacking canonical RAS mutations." (PMID 40362343, 2025). "Additionally, G3/G4 medulloblastoma-enriched H3K27me3 peaks exhibited a strong preference for gene promoters as compared to WNT/SHH." (PMID 39753768, 2025). "Malignant transformation of the human rhombic lip results in medulloblastoma, with group 3 (G3), group 4 (G4) and sonic hedgehog (SHH) tumors arising from the upper rhombic lip, and wingless/integrated (WNT) medulloblastoma arising from the lower rhombic lip1–13." (PMID 39753768, 2025). "Within the SHH subgroup, lower EPLIN expression was significantly associated with poorer overall survival (n = 172, p = 0.018), suggesting a potential subtype-specific role of EPLIN in medulloblastoma progression." (PMID 40701975, 2025). "In addition, the PDE4D inhibitor roflumilast suppresses the growth of medulloblastoma that is resistant to SHH antagonist vismodegib." (PMID 38233872, 2024). "Our results suggest that development of interventions promoting cilia deconstruction and centriole capping could restrict SHH responsiveness in treatment of medulloblastoma." (PMID 39705308, 2024). "Apart from targeting the SHH pathway itself at different levels, several groups have investigated the utility of targeting other pathways or effectors that are commonly overactivated in this subgroup of medulloblastomas." (PMID 37568705, 2023). "Although Shh pathway overactivation is clearly linked to medulloblastoma, the etiopathology of SHH-MB is mainly related to the mutation of Hedgehog pathway components rather than the amplification of the SHH gene, which represents only 3% of SHH-MB." (PMID 36672161, 2023). "Additional NGS was performed of 10 SHH-activated medulloblastomas." (PMID 36920679, 2023). "SHH-activated medulloblastoma have four molecular subgroups SHH-1, SHH-2, SHH-3, and SHH-4." (PMID 37509034, 2023). "All desmoplastic medulloblastomas belonged to the SHH-activated subtype." (PMID 36920679, 2023). "Notably, JQ1, a BRD4 inhibitor, was shown to inhibit the SHH-mediated proliferation of several tumors, including medulloblastomas, and to overcome their resistance to SMO antagonists." (PMID 37568705, 2023). "Based on findings from clinical-based studies, male-to-female ratios differ between molecular subgroups, with WNT and SHH groups showing approximately equal male and female distributions, but Group 3 and Group 4 medulloblastoma comprised with about twice as many males." (PMID 37035203, 2023). "However, hyperactivation of SHH signaling can transform CGNPs, resulting in medulloblastoma, a primitive neuro-ectodermal tumor that is the most common malignant pediatric brain tumor." (PMID 36635771, 2023).
medulloblastoma (continued). "Given that HH signaling plays a critical role in maintaining cancer stemness and progression of various diseases, further investigations are needed to explore how SCUBE2–HH signaling is involved in the progression of human pathologies, such as SHH-subgroup medulloblastoma." (PMID 37237303, 2023). "Specifically, we tested whether SMOi-resistant tumors containing SHH-dependent CSCs (SD-CSC) acquire new mutations in the SHH pathway, while SHH medulloblastomas containing SHH-independent CSCs (SI-CSC), that is, SI-CSC medulloblastomas, do not." (PMID 36688010, 2022). "The dual role of Nbs1 in Sonic Hedgehog (SHH)‐medulloblastoma (MB)." (PMID 35839783, 2022). "Comprising about 30% of medulloblastomas, SHH-driven tumors are the second most common subgroup." (PMID 35884462, 2022). "The glycogen synthase kinase-3 inhibitor, CHIR-98014, downregulates sonic hedgehog (SHH)-driven proliferation in cerebellar neurogenesis and may be useful in treating SHH-driven medulloblastomas." (PMID 35938030, 2022). "Remarkably, none of the seven LDE225-treated FSmoM2;hGFAP-cre medulloblastomas had acquired mutations in the SHH pathway." (PMID 36688010, 2022). "The presence of primary cilia is known to be associated with the molecular subgroups of human medulloblastoma; they are found in SHH and WNT subgroups but not in G3 and G4 subgroups, a finding that is well mirrored by mouse models of these subgroups." (PMID 35835507, 2022). "The Sonic hedgehog (SHH) subgroup of medulloblastoma, which accounts for 30% of all medulloblastoma cases, is believed to originate from the cerebellar granule neuron progenitor (CGNP) population that critically depends on SHH pathway signaling for its perinatal expansion." (PMID 35535520, 2022). "BET inhibition has also been shown to be a promising strategy in SHH-driven medulloblastoma." (PMID 35745584, 2022). "Some certain cancers including medulloblastoma (MB) and carcinoma basal cell are mediated by overactive SHH pathway; thus, in neurons, activation of SHH might induce neural recovery." (PMID 34981460, 2022). "WES detected an important PTCH1 germline variant in patient P46 with an SHH-activated medulloblastoma, which is not covered by the TSO500." (PMID 35475276, 2022). "Mutations of signaling molecules within the SHH pathway, such as SUFU, smoothened (SMO), PTCH1, GLI1 and GLI2, are defining, and they are commonly sought after as prime targets for small molecule inhibitors in medulloblastoma drug discovery." (PMID 35884462, 2022). "We hypothesized that SI-CSC medulloblastomas continue to grow in the presence of LDE225 by bypassing the SHH-dependent CGP-like cell state through epigenetic reprogramming of bulk tumor cells." (PMID 36688010, 2022). "In this review, we discuss the most recent studies regarding the roles of astrocytes in supporting sonic hedgehog (SHH) subgroup medulloblastoma (MB) and provide an overview of MB progression through SHH expression and signal transduction mechanisms into the complex tumor microenvironment." (PMID 34436033, 2021).
medulloblastoma (continued). "For example, the GTML (Glt1-tTA/TRE-MYCN-Luc) model in which MYCN aberration is driven by the glutamate transporter 1 (Glt1) promoter expressed in hindbrain progenitors develops tumors that closely resemble Group 3, but also shows the features of WNT, SHH, and Group 4 medulloblastoma." (PMID 33869004, 2021). "Therefore, the dysregulation of miRNAs’ activity is tumorigenic; for example, miR-326 downregulation promotes the SHH signaling pathway, which is responsible for medulloblastoma development." (PMID 34066495, 2021). "Looking at those patients who presented with an SHH activated medulloblastoma aged 3.5 years and younger as well as assuming SHH activation for all our Gorlin patients, approximately 17% of them would have tested positive for a pathogenic PTCH1 or SUFU mutation." (PMID 34888241, 2021). "More recently, studies have shown that YAP1 expression leads to upregulation of chromatin remodeler helicase, lymphoid specific (HELLS) in SHH-activated medulloblastoma and is activated downstream of SHH pathway activation through SMO, a positive transducer of SHH signaling." (PMID 34012965, 2021). "SHH dysregulation increases the risk of developing BCC, medulloblastoma, and meningioma." (PMID 33494284, 2021). "Thus, it is plausible that SHH and Group 3 medulloblastoma are intrinsically more dependent on CREB signaling and as a result have increased sensitivity to alterations in CREB activity." (PMID 34373489, 2021). "The SHH protein has been hypothesized to influence medulloblastoma in a paracrine manner by being secreted to the stroma which, in turn, signals to the tumor." (PMID 34436033, 2021). "SHH-activated medulloblastomas (SHH-MB) account for approximately 25% of all medulloblastomas." (PMID 34888241, 2021). "Additionally, Jones and colleagues detected a novel fusion transcript of DNAJB6 and SHH in one sample of SHH subgroup, and two further in-frame fusion transcripts in group 3 and group 4 medulloblastomas." (PMID 34830991, 2021). "Cerebellar developmental tumors such as medulloblastoma are among the most common malignant pediatric brain tumors that originate from cerebellar GC precursor cells due to impairment of several molecular pathways, including SHH and MycN." (PMID 33804256, 2021). "The pathogenesis of these tumors is distinct from BCC and medulloblastoma in that they do not present with any somatic mutational burden of the SHH pathway." (PMID 32957513, 2020). "Molecularly, SHH is the predominant group in adult medulloblastomas, while Group 3 is rare." (PMID 33172502, 2020). "Indeed, the use of the selective HDAC1/2 inhibitor mocetinostat inhibits HH signaling and reduces tumor growth in preclinical models of SHH-dependent medulloblastoma." (PMID 31244888, 2019). "High-throughput single-cell transcriptomic analysis of Sonic Hedgehog (SHH)-driven medulloblastomas before and after initiation of SHH inhibitor may determine whether intra-tumor heterogeneity contributes to the process of therapeutic failure." (PMID 31863004, 2019). "However, while vismodegib can induce initial responses in SHH-driven medulloblastoma, the long-term efficacy of vismodegib has been limited by the emergence of resistance during therapy." (PMID 31863004, 2019). "Aberrations in SHH signaling are well described in medulloblastoma." (PMID 31204176, 2019).